NAIP (NLR family apoptosis inhibitory protein)
Description:
Anti-apoptotic protein which acts by inhibiting the activities of CASP3, CASP7 and CASP9. Can inhibit the autocleavage of pro-CASP9 and cleavage of pro-CASP3 by CASP9. Capable of inhibiting CASP9 autoproteolysis at 'Asp-315' and decreasing the rate of auto proteolysis at 'Asp-330'. Acts as a mediator of neuronal survival in pathological conditions. Prevents motor-neuron apoptosis induced by a variety of signals. Possible role in the prevention of spinal muscular atrophy that seems to be caused by inappropriate persistence of motor-neuron apoptosis: mutated or deleted forms of NAIP have been found in individuals with severe spinal muscular atrophy. Acts as a sensor component of the NLRC4 inflammasome that specifically recognizes and binds needle protein CprI from pathogenic bacteria C.violaceum. Association of pathogenic bacteria proteins drives in turn drive assembly and activation of the NLRC4 inflammasome, promoting caspase-1 activation, cytokine production and macrophage pyroptosis. The NLRC4 inflammasome is activated as part of the innate immune response to a range of intracellular bacteria such as C.violaceum and L.pneumophila.
Synonyms: BIRC1; NLRB1; psiNAIP
Tractability: Small molecule: a structure with a bound ligand is known. PROTAC: its protein half-life has been measured.
Gene: Protein-coding gene on chromosome 5 (70,968,166 to 71,025,339, reverse strand). Ensembl gene ENSG00000249437.
Gene Ontology:
Molecular function: ATP binding; protein binding; protein serine/threonine kinase binding; cysteine-type endopeptidase inhibitor activity; cysteine-type endopeptidase inhibitor activity involved in apoptotic process
Biological process: negative regulation of apoptotic process; negative regulation of tumor necrosis factor-mediated signaling pathway; positive regulation of JNK cascade; regulation of apoptotic process; defense response to bacterium; detection of bacterium; icosanoid biosynthetic process; negative regulation of neuron apoptotic process; nervous system development; pattern recognition receptor signaling pathway; positive regulation of inflammatory response; positive regulation of interleukin-1 beta production; pyroptotic inflammatory response
Cellular component: basolateral plasma membrane; canonical inflammasome complex; cytoplasm; IPAF inflammasome complex
Genetic constraint (gnomAD): Loss-of-function variants: 15 observed, 22.89 expected, observed/expected ratio (o/e) 0.66, 90% interval 0.44 to 1.01. The upper end of that interval is the gene's LOEUF score, 1.01, which puts it in group 4 of 6, group 1 being the genes least tolerant of losing a copy. Missense variants: 265 observed, 276.87 expected, observed/expected ratio (o/e) 0.96, 90% interval 0.87 to 1.06. Synonymous variants: 100 observed, 99.75 expected, observed/expected ratio (o/e) 1, 90% interval 0.85 to 1.18.
Homologues: Orthologues: chimpanzee NAIP (99% identical), macaque NAIP (92% identical), tropical clawed frog naip.2 (38% identical), tropical clawed frog naip.3 (10% identical), Drosophila melanogaster Diap2 (9% identical), Caenorhabditis elegans bir-2 (6% identical). Paralogues in human: BIRC6 (15% identical), NLRC4 (13% identical), BIRC2 (12% identical), BIRC3 (11% identical), XIAP (9% identical), BIRC7 (6% identical), BIRC5 (3% identical).
Diseases named in the same sentence as NAIP in open-access papers:
NAIP is named in the same sentence as 61 diseases in open-access papers, as found by Europe PMC text mining. Sharing a sentence is not in itself a finding about the gene and the disease. The quoted sentences say what the papers report.
spinal muscular atrophy (13 papers, 2009 to 2024). A motor neuron disease that affect the muscles, and characterized by muscle weakness and atrophy resulting from progressive degeneration and irreversible loss of the anterior horn cells in the spinal cord (i.e., lower motor neurons) and the brain stem nuclei. "Classified as a Tenuous gene by ALSoD, CNVs on NAIP were associated with severe and acute forms of spinal muscular atrophy (SMA) and considered as secondary ‘passenger’ events in ALS pathogenesis." (PMID 39066921, 2024). "NAIP was first discovered as spinal muscular atrophy (SMA) related gene whose deletion or mutation was restricted to SMA patients." (PMID 33557398, 2021). "Deficiency of NAIP is associated with the most severe types of spinal muscular atrophy, a hereditary neurodegenerative disorder." (PMID 25344864, 2014). "Then, mutation in the NAIP has been linked to development of spinal muscular atrophy (SMA), which is a progressive motor neurodegenerative disorder." (PMID 22357131, 2012). "The NAIP gene first rose to prominence when it was cloned as a putative disease allele for the neurodegenerative disorder, Spinal Muscular Atrophy (SMA), but is now understood to influence SMA severity, which is induced by the adjacent SMN gene." (PMID 19488400, 2009). "The BIRC1 gene encodes the neuronal apoptosis inhibiting protein (NAIP) and it is a modifier of spinal muscular atrophy resulting from a mutation in a neighboring SMN1 (Survival of Motor Neuron 1) gene." (PMID 33673050, 2021). "Spinal muscular atrophy (SMA) is caused by SMN1 dysfunction, and the copy number of SMN2 and NAIP can modify the phenotype of SMA." (PMID 25888055, 2015). "Neuronal apoptosis inhibitory protein (NAIP), which is thought to be a modifier gene for spinal muscular atrophy, is a founding member of the inhibitor of apoptosis." (PMID 29311650, 2018). "NAIP is a member of the inhibitor of apoptosis protein (IAP) family, and was cloned as a candidate gene for the neurodegenerative disorder Spinal Muscular Atrophy (SMA)." (PMID 19488400, 2009). "In spinal muscular atrophy (SMA), neuron-specific IAP family members NAIP and XIAP effectively block the enzymatic activity of group II caspases (3 and 7) and reduce the expression levels of cleaved-caspase-3, thereby protecting spinal motor neurons (MNs) and preventing severe SMA." (PMID 39337436, 2024).
melanoma (12 papers, 2008 to 2024). A malignant, usually aggressive tumor composed of atypical, neoplastic melanocytes. "In this study, the transcript levels of IAP genes including NAIP (BIRC1), BIRC2 (CIAP1), BIRC3 (CIAP2), BIRC5 (Survivin), BIRC6 (Apollon), and XIAP (BIRC4) in UA-treated A-375 melanoma cells were investigated." (PMID 39473730, 2024). "These are X-linked inhibitor of apoptosis protein (XIAP), cellular IAP 1 (cIAP1), cellular IAP 2 (cIAP2), IAP-like protein 2 (ILP-2), melanoma IAP (ML-IAP), neuronal apoptosis inhibitory protein (NAIP), Apollon and Survivin." (PMID 35568716, 2022). "Particularly well-characterized members of this family include XIAP (X-chromosome-linked IAP), cIAP1 (cellular IAP1), cIAP2 (cellular IAP2), Apollon, ML-IAP (melanoma IAP), survivin, IAP-like protein 2 (ILP2), and NAIP (neuronal apoptosis inhibitory protein)." (PMID 24531137, 2014). "XIAP is a ubiquitously expressed protein and a member of the inhibitor of apoptosis (IAP) family, which also includes cellular IAP1 (cIAP1), cellular IAP2 (cIAP2), melanoma IAP (ML-IAP), neuronal apoptosis inhibitory protein (NAIP), survivin, Appolon and IAP-like protein 2 (ILP2)." (PMID 36270981, 2022). "Pattern recognition receptors involved in inflammasomes comprise nucleotide-binding oligomerization domain and leucine-rich repeat-containing receptors (NLR) such as NLRP3 and NAIP, as well as absent in melanoma-2 (AIM-2)." (PMID 32431703, 2020). "Substantial evidence now exists to support a protective role for NAIP/NLRC4 against the infection with Salmonella typhimurium in vivo, respiratory melioidosis; however, NAIP/NLRC4 inflammasome does not protect against melanoma." (PMID 32630319, 2020).
breast carcinoma (8 papers, 2010 to 2024). "In breast cancer survivin and NAIP overexpression has been associated in unfavourable clinical features." (PMID 20078866, 2010). "A study showed that NAIP was expressed in breast cancer and at significantly higher levels than in tumor control groups." (PMID 37020871, 2023). "Little is known about NAIP’s role in breast cancer, but NAIP mRNA levels have been well detected in tumor samples, while no expression is observed in control tissues." (PMID 30837326, 2019). "So far, high level expression of NAIP has been reported in prostate cancer cell line, breast cancer patients and bone marrow of AML." (PMID 22357131, 2012). "More mechanistic studies are still warranted to confirm whether NAIP is relevant to breast cancer biology." (PMID 30837326, 2019). "Also, NAIP overexpression in breast cancer samples of patients with unfavorable clinical features was detected using quantitative RT-PCR and it was suggested that NAIP would play a role in disease progression." (PMID 22357131, 2012). "However, little is known about the clinical relevance of NAIP expression in breast cancer and in our knowledge no report described the presence in human prostate tissue." (PMID 20078866, 2010).
prostate carcinoma (6 papers, 2010 to 2022). A carcinoma that arises from epithelial cells of the prostate gland. "In advanced prostate cancer, elevated NAIP is an early event, and its cytoprotective effects are associated with the NFkB-1 transcription factor signaling pathway." (PMID 31269724, 2019). "These novel findings suggest the importance of NAIP in sensitizing prostate cancer cells to immune-mediated attack and warrant further studies in other carcinomas." (PMID 25344864, 2014). "The functional importance of NAIP in immunogenic modulation was confirmed by demonstrating that a reduction in NAIP, whether mediated by treatment with enzalutamide or NAIP siRNA, in either AR+ or AR− prostate cancer cells, improved the cells' sensitivity to T cell-mediated killing." (PMID 25344864, 2014). "High level expression of NAIP along with SURVIVIN, cIAP-1, cIAP-2 and XIAP were reported in prostate cancer cell line." (PMID 22357131, 2012). "Percentages of patients showing positive immunohistochemical reactions to NAIP, Survivin and XIAP in normal prostate (NP), benign prostatic hyperplasia (BPH), prostatic carcinoma (PC) average optical densities of immunostaining in positive patients." (PMID 20078866, 2010). "Protein expression of caspases (procaspase-8, cleaved caspase-8, procaspase-3, cleaved caspase-3, caspase-7 and procaspase-9) and IAPs (cIAP1/2, cIAP2, NAIP, Survivin and XIAP) was analyzed by immunohistochemistry in radical prostatectomy samples from 84 prostate cancer patients." (PMID 26507126, 2015). "The exact mechanism of NAIP involvement in prostate cancer progression has not been determined." (PMID 25344864, 2014). "There were no previous descriptions for the fusions NAIP:OCLN, PDE1C:DNAJC6, KANSL1:ARL17B, FOXP2:CREM, and AHSA1:DLG3 in the context of prostate cancer." (PMID 35625354, 2022).
Salmonella Infections (6 papers, 2021 to 2025). Infections with bacteria of the genus SALMONELLA. "Our studies uncover a multifaceted inflammasome response to Salmonella infection in human macrophages, and reveal that NAIP/NLRC4 inflammasome-dependent sensing of the SPI-2 T3SS promotes control of intracellular Salmonella." (PMID 35073381, 2022). "In contrast, Salmonella infection induced activation of inflammasome responses that depended on the collective responses of NAIP/NLRC4, NLRP3, and CASP4/5." (PMID 35073381, 2022). "Salmonella infection induces NAIP/NLRC4-, CASP4/5-, and NLRP3-dependent inflammasome activation in human macrophages." (PMID 35073381, 2022). "Altogether, these data indicate that Salmonella infection induces both NAIP/NLRC4- and NLRP3-dependent inflammasome activation in human macrophages, in agreement with previous studies." (PMID 35073381, 2022). "The NAIP/NLRC4 inflammasome promotes control of intestinal Salmonella infection in mice by triggering pyroptosis and expulsion of infected intestinal epithelial cells." (PMID 35073381, 2022). "The role of NAIP/NLRC4 or other inflammasomes during Salmonella infection of human macrophages is unclear." (PMID 35073381, 2022). "In mice, the NAIP/NLRC4 inflammasome is required to control Salmonella infection." (PMID 40162563, 2025). "In mice, intestinal epithelial cells (IECs) are a primary site of Salmonella infection, and epithelial-intrinsic expression of NAIP or NLRC4 is both necessary and sufficient to restrict bacterial burden, indicating a central role for the NAIP/NLRC4 inflammasome in mucosal immunity." (PMID 41304196, 2025). "In murine macrophages, Salmonella infection activates both the NAIP/NLRC4 and NLRP3 inflammasomes." (PMID 35073381, 2022). "Overall, these data indicate that Salmonella infection of human macrophages triggers activation of multiple inflammasomes, and at least two of these inflammasomes, the NAIP/NLRC4, and the NLRP3 inflammasomes, appear to be essential for controlling bacterial replication within macrophages." (PMID 35073381, 2022). "Because S. Typhimurium induces PANoptosis and previous studies have clearly shown that the NAIP/NLRC4 inflammasome is activated during Salmonella infection, it is highly likely that the NAIP/NLRC4 inflammasome contributes to PANoptosis during bacterial infection." (PMID 33494299, 2021). "While the precise nature of this interaction is still a subject of debate, it has been suggested that the NAIP/NLRC4/ASC complex formed after Salmonella infection may recruit NLRP3, potentially amplifying caspase-1 cleavage and subsequent IL-1β cytokine release." (PMID 38124741, 2023). "Human macrophages undergo NAIP/NLRC4- and NLRP3-dependent inflammasome activation during Salmonella infection, which restricts intracellular Salmonella replication." (PMID 40162563, 2025). "Recently, both the NAIP/NLRC4 and NLRP3 (NLR pyrin domain-containing protein 3) inflammasomes have been shown to respond to Salmonella infection in human macrophages." (PMID 35073381, 2022). "In this study, we found that while human macrophages require both NAIP and NLRC4 for inflammasome responses to T3SS ligands, NAIP and NLRC4 are only partially required for the inflammasome response during Salmonella infection." (PMID 35073381, 2022). "In mice, in addition to the NAIP/NLRC4 and NLRP3 inflammasomes, Salmonella infection can also activate the caspase-11 inflammasome." (PMID 35073381, 2022). "We find that while NAIP is necessary to detect individual T3SS ligands, it is only partially required for inflammasome responses to Salmonella infection in human macrophages." (PMID 35073381, 2022). "In human THP-1s, Salmonella infection triggers recruitment of both NLRC4 and NLRP3 to the same macromolecular complex, and the NAIP and NLRP3 inflammasomes both contribute to inflammasome responses to Salmonella." (PMID 35073381, 2022).
Salmonella Infections (continued). "Overall, these data indicate that NAIP and NLRC4 are partially required for inflammasome responses to Salmonella infection in human macrophages, in contrast to what we observe with individual T3SS ligand delivery, where NAIP/NLRC4 is absolutely required for inflammasome activation." (PMID 35073381, 2022). "In mice, the NAIP/NLRC4 inflammasome is important for controlling Salmonella replication in the intestine, whereas the NLRP3 inflammasome is dispensable for control of Salmonella infection in vivo." (PMID 35073381, 2022).
Sepsis (4 papers, 2021 to 2025). Sepsis is defined as life-threatening organ dysfunction caused by a dysregulated host response to infection. "Our findings elucidate a molecular mechanism of ARF in sepsis and contribute to an enhanced understanding of the (patho)physiological role of the NAIP/NLRC4 inflammasome." (PMID 40158217, 2025). "Eight genes (CLEC5A, MALT1, NAIP, NLRC4, SERPINB1, SIRT1, STAT3, and TLR2) related to sepsis diagnosis were screened by multiple machine learning algorithms." (PMID 36817458, 2023). "In keeping with a role for regulators of apoptosis in the pathogenesis of sepsis, members of the IAP family, including NAIP/BIRC1 and BIRC3, are downregulated in immune cells in patients with sepsis, as is the BIRC6 ubiquitination target SMAC." (PMID 35866869, 2022). "It is tempting to speculate that NLRP3 activation can complement inefficient NAIP/NLRC4 activation in human macrophages under certain conditions, for example in sepsis when LPS levels are high, as our mRNA expression data suggests NLRC4 expression is lowered under these conditions." (PMID 33380493, 2021).
bacillary dysentery (3 papers, 2021 to 2022). "Considering that NAIP/NLRC4-deficient mice are susceptible to shigellosis, the cell-autonomous immune response driven by the NAIP/NLRC4 inflammasome is probably a main factor underlying the resistance of wild-type mice to S. flexneri infection." (PMID 35801644, 2022). "However, recent data showed that C57BL/6J, C57BL/6N and 129S1/SvImJ mice that lack the NAIP/NLRC4 inflammasome can develop shigellosis-like phenotypes." (PMID 35801644, 2022). "Diarrhea in dogs, often associated with bacterial enteropathogens, is one of the most common clinical conditions encountered by veterinarians, and Shigella infection of mice lacking NAIP/NLRC4 in their intestinal epithelial cells induces a bacillary dysentery." (PMID 34433041, 2021).
amyotrophic lateral sclerosis (2 papers, 2018 to 2021). Amyotrophic lateral sclerosis (ALS) is a neurodegenerative disease characterized by progressive muscular paralysis reflecting degeneration of motor neurons in the primary motor cortex, corticospinal tracts, brainstem and spinal cord. "However, comprehensive studies over the last years indicate the relevance of NAIP in a variety of different molecular mechanisms and diseases such as cytokinesis, inflammasome formation, amyloid-β toxicity, amyotrophic lateral sclerosis (ALS) and Parkinson’s disease." (PMID 33557398, 2021).
COVID-19 (2 papers, 2022 to 2024). A disease caused by infection with severe acute respiratory syndrome coronavirus 2. "The increased expression of selected IFN-I (OAS1, OAS2, and IFIT1) and inflammasome related genes (CASP1, CASP5, NLRC5 and NAIP) between COVID-19 and HC PMNs was confirmed by RT-qPCR." (PMID 39172744, 2024). "Similar to the mDC subsets, the NLRP1, AIM2, NAIP expression was also highly activated pDCs from the in COVID-19 groups." (PMID 36439166, 2022).
glioma (2 papers, 2019 to 2024). A benign or malignant brain and spinal cord tumor that arises from glial cells (astrocytes, oligodendrocytes, ependymal cells). "Furthermore, the expression levels of genes encoding NLR proteins (NLRP12, NOD2, NOD1, NLRC4, and NAIP), inflammasome adaptor molecules (PYCARD), and proinflammatory caspases (CASP1, CASP4, and CASP5) were significantly higher in glioma patients than in normal controls." (PMID 31133717, 2019).
lung carcinoma (2 papers, 2022 to 2026). "This study utilized immunoinformatics and structural bioinformatics approaches to design and evaluate a multi-epitope vaccine targeting pyroptosis-associated antigens (CARD8, NAIP, NLRP1, and NLRP3), which are implicated in lung cancer immunology." (PMID 41857073, 2026).